CNDP1 (carnosine dipeptidase 1)
Description:
Catalyzes the peptide bond hydrolysis in Xaa-His dipeptides, displaying the highest activity toward carnosine (beta-alanyl-L-histidine).
Synonyms: CN1; CPGL2; MGC10825; HsT2308
Tractability: Small molecule: it has a high-quality binding pocket. Antibody: UniProt places it where antibodies can reach, with high confidence; UniProt predicts a signal peptide or a membrane-spanning region; its Gene Ontology location is reachable by antibodies, with medium confidence.
Gene: Protein-coding gene on chromosome 18 (74,534,400 to 74,587,212, forward strand). Ensembl gene ENSG00000150656.
Subcellular location: Secreted
Gene Ontology:
Molecular function: aminopeptidase activity; carboxypeptidase activity; dipeptidase activity; metallodipeptidase activity; protein binding; hydrolase activity
Biological process: proteolysis; regulation of protein metabolic process
Cellular component: cytosol; extracellular region
Genetic constraint (gnomAD): Loss-of-function variants: 38 observed, 52.77 expected, observed/expected ratio (o/e) 0.72, 90% interval 0.56 to 0.94. The upper end of that interval is the gene's LOEUF score, 0.94, which puts it in group 4 of 6, group 1 being the genes least tolerant of losing a copy. Missense variants: 557 observed, 623.02 expected, observed/expected ratio (o/e) 0.89, 90% interval 0.83 to 0.96. Synonymous variants: 238 observed, 244.27 expected, observed/expected ratio (o/e) 0.97, 90% interval 0.88 to 1.09.
Homologues: Orthologues: chimpanzee CNDP1 (97% identical), macaque CNDP1 (95% identical), dog CNDP1 (82% identical), rabbit CNDP1 (82% identical), pig CNDP1 (82% identical), guinea pig CNDP1 (81% identical), rat Cndp1 (78% identical), mouse Cndp1 (77% identical), tropical clawed frog cndp1 (60% identical). Paralogues in human: CNDP2 (49% identical), PM20D1 (17% identical), ACY1 (15% identical).
Diseases named in the same sentence as CNDP1 in open-access papers:
CNDP1 is named in the same sentence as 61 diseases in open-access papers, as found by Europe PMC text mining. Sharing a sentence is not in itself a finding about the gene and the disease. The quoted sentences say what the papers report.
diabetic nephropathy (24 papers, 2013 to 2026). "In the past years the CNDP1 gene, encoding CN-1, has attracted much attention as susceptibility locus for diabetic nephropathy (DN) in type 2 diabetic patients." (PMID 26799971, 2016). "The susceptibility to diabetic nephropathy is strongly associated with a polymorphism in the CNDP1 gene." (PMID 24566305, 2014). "The results indicated that 2 SNPs in CNDP1, rs12604675 and rs733686, were nominally associated with diabetic nephropathy only in women." (PMID 23342076, 2013). "Carnosine has been reported to protect against renal injury, along with having antioxidant activity, inhibition of AGE formation, and ACE inhibition property, suggesting that CNDP1 contributes to conferring susceptibility to diabetic nephropathy." (PMID 23342076, 2013). "In this study, we examined the association of polymorphisms within the CNDP1/CNDP 2 locus with diabetic nephropathy in Japanese subjects with type 2 diabetes." (PMID 23342076, 2013). "A trinucleotide repeat (leucine repeat) polymorphism, D18S880, in exon 2 of CNDP1 was previously reported to be associated with diabetic nephropathy." (PMID 23342076, 2013). "Many genetic loci, including the carnosinase dipeptidase 1 (CNDP1) gene, have been reported to play a role in susceptibility to develop diabetic kidney disease (DKD)." (PMID 36319874, 2023). "Moreover, a polymorphism in the CNDP1 gene ("Mannheim allele") encoding serum carnosinase CN1 with reduced enzymatic activity is associated with a reduced risk of developing diabetic nephropathy." (PMID 35294673, 2022). "Several linkage analyses have mapped a susceptibility locus for diabetic nephropathy to chromosome 18q22–23, and polymorphisms within the carnosine dipeptidase 1 gene (CNDP1), located on 18q22.3, have been shown to be associated with diabetic nephropathy in European subjects with type 2 diabetes." (PMID 23342076, 2013). "We next examined the association of 29 SNPs within the CNDP1/CNDP2 locus with diabetic nephropathy." (PMID 23342076, 2013). "Though it remains unknown why the association of CNDP1 SNPs with diabetic nephropathy was observed only in women, there are several reports demonstrating that the effects of CNDP1 variants are more significant in women than in men." (PMID 23342076, 2013). "Therefore, CNDP1 is considered to be a plausible susceptibility gene candidate for diabetic nephropathy in this locus." (PMID 23342076, 2013). "Prompted by the finding that the carnosinase 1 gene (CNDP1) is a susceptibility locus for developing diabetic kidney disease (DKD) in patients with type 2 diabetes, various studies have reported possible mechanisms by which carnosine may convey protection against DKD." (PMID 38960916, 2024). "CNDP1 is a marker for diabetic nephropathy and cardiovascular mortality in female patients with type 2 diabetes mellitus." (PMID 38500750, 2024). "We and others have previously reported that a polymorphism in the CNDP1 gene, encoding serum carnosinase-1 (CN1), is associated with lower risk of developing diabetic nephropathy in patients with type 2 diabetes." (PMID 34356335, 2021). "Diabetic patients homozygous for 5-Leu type of CNDP1 are protected against diabetic nephropathy, because carnosine acts as a protective factor against adverse effects of high glucose levels on renal cells." (PMID 24566305, 2014). "In this study, we examined the association of polymorphisms within the CNDP1/CNDP2 locus, D18S880 and 29 single nucleotide polymorphisms (SNPs), with diabetic nephropathy in Japanese subjects with type 2 diabetes." (PMID 23342076, 2013). "The case-control study among diabetic patients with and without diabetic nephropathy showed a significant association with diabetic nephropathy in CNDP1, NOS3, and MnSOD genes." (PMID 37187702, 2023).
diabetic nephropathy (continued). "In the present study, we assessed if the association between CNDP1 and DN is still observed when applying CIC or biopsy-proven diabetic nephropathy (BP-DN) and, if so, whether this is only observed in female T2DM patients." (PMID 28553654, 2017). "Whether the Cndp1-KO related changes in cellular protective mechanisms and the renal accumulation of carnosine and anserine provide a significant protection against diseases such as diabetic nephropathy, remains to be investigated in respective animal models." (PMID 32664451, 2020). "The enzyme CNDP1 has been mentioned concerning T2DM, where carnosine acted as a protective factor in diabetic nephropathy." (PMID 32326243, 2020).
diabetes (13 papers, 2014 to 2026). "Our results are consistent with those of another study indicating that overexpression of CNDP1, the metabolic enzyme of carnosine, is associated with a risk for poor diabetes control (and a high risk for T2DM and DKD)." (PMID 37736814, 2023). "We defined T2D-ESKD candidate loci as genes which have been implicated in ESKD (diabetes associated or non-diabetes associated) either through direct (e.g. CNDP1, APOL1) genetic analysis or through compelling functional relationships (e.g. REN)." (PMID 24551085, 2014). "Association of CNDP1 with diabetes mellitus has been widely demonstrated in many papers." (PMID 32326243, 2020). "The in vivo relevance of these interactions is demonstrated in Hsp70- and Cndp1-KO mice, but awaits clarification in diabetes mellitus and ischemic heart disease." (PMID 36670928, 2022). "This conclusion partially supported the notion that CNDP1 overexpression accelerated the development of diabetes and DN." (PMID 33811534, 2021). "SHBG and PRSS2 might explain the beneficial association with IHD; testosterone, SHBG, CCL5, CNDP1, F11, LCN2, and THBS4 might explain the association with diabetes, which provides insights for drug development." (PMID 41882153, 2026). "The impact of diabetes mellitus was demonstrated in type 1 diabetic Cndp1-KO mice." (PMID 36670928, 2022). "In patients with type 2 diabetes mellitus (DM), especially in females, we and others demonstrated an association of the susceptibility to develop diabetic nephropathy (DN), with a variant in the carnosinase 1 gene (CNDP1), associated with lower carnosinase 1 (CN1) activity." (PMID 30217069, 2018). "In keeping with the recently published prospective study that the CNDP1 genotype may impart a cardiovascular mortality risk in female, but not in male T2DM patients, we investigated whether genotype distribution changes with time on dialysis or diabetes duration." (PMID 28553654, 2017). "Intraperitoneal insulin and glucose tolerance (week 30) were not different between Cndp1-KO and WT mice with diabetes and normal glucose homeostasis, on ND and HFD, respectively." (PMID 37372000, 2023). "In the Cndp1-KO mice on ND, the high kidney anserine and carnosine concentrations prevented the 1.5-fold increase in AGE and 4-fold increase in 4-HNE concentrations observed in the diabetic WT littermates, i.e., counteracted the tissue glycative and oxidative stress of diabetes." (PMID 37372000, 2023). "Thus, the type 1 diabetes mellitus Cndp1-KO model does not allow for firm conclusions on their interaction." (PMID 36670928, 2022).
type 2 diabetes (13 papers, 2013 to 2026). "We and others have previously reported that the CNDP1 (CTG)n polymorphism is associated with susceptibility to develop DKD in patients with type 2 diabetes." (PMID 32803273, 2020). "Another study in American Indians with type 2 diabetes found nominal association of 2 SNPs within CNDP1, rs12957330 and rs17817077, with ESRD." (PMID 23342076, 2013). "Carnosine dipeptidase 1, a member of the M20 metalloprotease family, has yet to be described in relation to AAAs but has previously been associated with an increased risk of nephropathy in type 2 diabetes patients." (PMID 39728917, 2024). "Rs12604675-A in CNDP1 may confer susceptibility to overt proteinuria in Japanese women with type 2 diabetes." (PMID 23342076, 2013).
Nephropathy (11 papers, 2013 to 2024). A nonspecific term referring to disease or damage of the kidneys. "Another polymorphism that had shown association with nephropathy is at the promoter region of CNDP1 identified as rs2346061." (PMID 30719346, 2019). "We previously demonstrated that polymorphisms in the carnosinase-1 gene (CNDP1) determine the risk of nephropathy in type 2 diabetic patients." (PMID 28281693, 2017). "In addition, it should be of great interest to study the impact of reduced glycative and oxidative stress in the diabetic kidney of the Cndp1-KO mice on mitochondrial dysfunction, which has been implicated in kidney fibrosis and progression of kidney disease." (PMID 37372000, 2023). "Low serum carnosine dipeptidase-1 (CNDP1) gene polymorphism protects patients with T2D against diabetic complications including nephropathy and can be allosterically blocked by the injection of reduced glutathione (GSH), N-acetylcysteine, and cysteine in diabetic mice." (PMID 35268685, 2022). "Further studies are required, in particular in mice with renal diseases, to demonstrate whether the Cndp1-KO associated changes in specific amino acids are of pathophysiological relevance." (PMID 32664451, 2020). "Diabetic patients with Cndp1 gene variants, which are associated with a lower serum CN1 activity, have a lower risk of nephropathy." (PMID 36670928, 2022). "By utilizing a custom target NGS 70-gene panel and a validation cohort, we have been able to point out some of these rare variants in the MYH9, CNDP1, SOWAHB and RGMA genes relevant to renal disease in diabetic patients." (PMID 34946941, 2021). "For the carnosinase gene (CNDP1), D18S880 genotype associated with nephropathy in the Malays (p=0.026), Chinese (p=0.0171), and Indians (p=0.0095), as supported by the alleles in Malays (p=0.0004), Chinese (p=0.0019), and Indians (p=0.0055)." (PMID 30719346, 2019). "Later studies on chromosome 18 led to the identification of a susceptibility marker within the carnosine dipeptidase 1 (CNDP1) gene, and it was also described how the shortest allelic form of the CNDP1 gene was more common in the absence of nephropathy." (PMID 26798653, 2016). "Additionally, in a prospective study of pediatric patients with non-diabetic nephropathies, the CNDP1 polymorphism was found to correlate with renal survival, particularly in patients with glomerulopathies." (PMID 34356335, 2021).
type 1 diabetes (6 papers, 2019 to 2025). "Because the incidence of ESRD attributable to both Type 1 diabetes (T1DM) and T2DM is higher among South Asian than Caucasian people, the present study assessed relevant CNDP1 polymorphisms and their association with metabolic parameters in the Chinese Han population." (PMID 32733966, 2020). "Global carnosinase-1 knockout mice (Cndp1-KO) and wild-type littermates (WT) on a normal diet (ND) and high fat diet (HFD) (n = 10/group), with streptozocin (STZ)-induced type-1 diabetes (n = 21–23/group), were studied for 32 weeks." (PMID 37372000, 2023).
chronic kidney disease (5 papers, 2013 to 2021). Impairment of the renal function secondary to chronic kidney damage persisting for three or more months. "CN-1 gained scientific prominence by the finding that polymorphisms in the CNDP1 gene may affect chronic kidney disease in diabetic and nondiabetic patients." (PMID 32733966, 2020).
glioblastoma (3 papers, 2014 to 2019). The most malignant astrocytic tumor (WHO grade IV). "Very recently, reduced levels of CNDP1 were observed in 8 out of 10 plasma specimens of patients with glioblastoma (GBM)." (PMID 24566305, 2014). "This approach identified a small set of differentially expressed proteins among which Carnosine Dipeptidase 1 (CNDP1), a protein recently shown to be reduced in metastatic prostate cancer and glioblastoma, was confirmed by sandwich immunoassay to be reduced in CC." (PMID 25898255, 2015). "Furthermore, a recent proteomic analysis using a non-immune-based (liquid chromatography-tandem mass spectrometry) approach suggested that CNDP1 is one of several proteins down regulated in plasma of ten patients with glioblastoma compared with healthy controls." (PMID 25898255, 2015).
hepatocellular carcinoma (3 papers, 2023 to 2024). A malignant tumor that arises from hepatocytes. "Down-regulation of CNDP1 was associated with cancer cachexia, and it was recently reported that CNDP1 level was significantly reduced in hepatocellular carcinoma tissues." (PMID 38383428, 2024). "Moreover, we undertook an association analysis concerning the expression of CNDP1 with immune infiltration, along with survival analysis across various cancers and specifically in hepatocellular carcinoma (HCC)." (PMID 38883336, 2024). "By delving into the mechanisms of AS-IV, this study elucidates how it weakens PD-L1-mediated immune suppression through the miR-135b-5p/CNDP1 axis, potentially representing a key mechanism for AS-IV in anti-hepatocellular carcinoma (HCC) therapy." (PMID 37894415, 2023).
prostate carcinoma (3 papers, 2015 to 2024). A carcinoma that arises from epithelial cells of the prostate gland. "Low CNDP1 levels have been found to be associated with lymph node metastasis in a large cohort of prostate cancer patients." (PMID 25898255, 2015).
Cachexia (2 papers, 2017 to 2021). Severe weight loss, wasting of muscle, loss of appetite, and general debility related to a chronic disease. "A study involving gastrointestinal cancer patients with and without cachexia showed that the plasma level of carnosine dipeptidase 1 (CNDP1) is significantly lower in cachexia patients." (PMID 33925872, 2021).
Insulin resistance (2 papers, 2020 to 2025). Increased resistance towards insulin, that is, diminished effectiveness of insulin in reducing blood glucose levels. "Based on the evidence that anaerobic glycolysis retained an increasing rate in patients with T2DM and GDM, increased lactate producing and stressing of CNDP1, we assumed the involvement of carnosinase and its substrate in the proposed mechanism of insulin resistance." (PMID 32326243, 2020).
Obesity (2 papers, 2020 to 2025). Accumulation of substantial excess body fat. "Cndp1-KO zebra fish have increased carnosine concentrations, and exhibit less body weight gain with high-fat diet than the respective WT fish and a combination of genetic variations in CNDP1 and CNDP2 were associated with obesity risk in Japanese men." (PMID 32664451, 2020). "The following seven proteins are present in higher amounts in the Obesity group compared with the Control group: hemopexin—HPX, complement factor B—CFB, complement C3—C3, kininogen-1—KNG1, vitronectin—VTN, pigment epithelium-derived factor—SERPINF1 and beta-Ala-His dipeptidase—CNDP1." (PMID 41441338, 2025).
pancreatic cancer (2 papers, 2015 to 2023). "Model 3 primarily includes CARNS1, CNDP1, GATM, and ABAT, which are mainly distributed in tumors, particularly pancreatic cancer and breast cancer." (PMID 36914737, 2023). "In order to validate but also to better define the association between reduced CNDP1 levels and prognosis, circulating CNDP1 was determined by SIA in a separate, more homogenous, validation cohort including only subjects with advanced pancreatic cancer (Cohort 2)." (PMID 25898255, 2015).
acute leukemia (1 paper, 2015). A clonal (malignant) hematopoietic disorder with an acute onset, affecting the bone marrow and the peripheral blood. "Thus, reduced CNDP1 levels have been reported in different aggressive cancer forms while APOA4 has been shown to be increased in pediatric forms of high risk acute leukemia but lower in adult women with ovarian cancer." (PMID 25898255, 2015).
acute myeloid leukemia (1 paper, 2024). Acute myeloid leukemia (AML) is a group of neoplasms arising from precursor cells committed to the myeloid cell-line differentiation. "Our findings revealed a positive correlation between CNDP1 expressions in BLCA, CHOL, COAD, ESCA, HNSC, KIRP, acute myeloid leukemia, and LUAD with TMB values." (PMID 38883336, 2024).
brain ischemia (1 paper, 2019). Diminished or absent blood supply to the brain caused by obstruction (thrombosis or embolism) of an artery resulting in neurologic damage. "Thus, we concluded that CEA significantly affects serum CNDP1 and UCHL1 concentrations, and therefore these enzyme concentrations seem to reflect brain ischemia resulting from severe internal carotid artery stenosis in patients undergoing CEA." (PMID 31460820, 2019).
cerebrovascular disease (1 paper, 2024). "The reductions of CNDP1 protein we observed parallels reports of reduced enzymatic activity in cases of multiple sclerosis, Parkinson’s disease, and cerebrovascular disease." (PMID 38880880, 2024).
colorectal cancer (1 paper, 2024). A primary or metastatic malignant neoplasm that affects the colon or rectum. "log(P/(1-P) = -7.8709 + 4.5956 × IGFBP2 + 0.2732 × ITIH3 + 0.0909 × LRG1 + 0.1015 × C9 -3.2205 × CNDP1 + 0.0239 × ORM1 + 0.0811 × SERPINA1, where P is a value between 0 and 1 that represents the probability of the event (colorectal cancer)." (PMID 38383428, 2024).
endometrial cancer (1 paper, 2024). Primary or metastatic malignant neoplasm involving the endometrium (mucous membrane that lines the endometrial cavity). "For plasma proteins, a 4-marker panel combining CNDP1, CDC5L, APOD and PRDX6 had the least AIC value and predicted early-stage endometrial cancer with an AUC of 0.88 (0.82–0.95)." (PMID 38513301, 2024).
immune complex disease (1 paper, 2023). "Genes involved in the complement cascade including glycosylphosphatidylinositol-specific phospholipase D1 (GPLD1), carnosine dipeptidase 1 (CNDP1) (in KEGG only), superoxide dismutase 3 (SOD3), and butyrylcholinesterase (BCHE) were also prominent in this immune complex disease." (PMID 37238213, 2023).